HSPB6 (heat shock protein family B (small) member 6)
Diseases named in the same sentence as HSPB6 in open-access papers (continued):
Sharing a sentence is not in itself a finding about the gene and the disease.
Granuloma (1 paper, 2020). A compact, organized collection of mature mononuclear phagocytes, which may be but is not necessarily accompanied by accessory features such as necrosis. "Only six genes (ADAMTS1, HSPB6, NR4A1, CXCL2, NPR1, ITGA9) were exclusively dysregulated in both lung and lymph node in sarcoidosis granulomas but not in CM or TB." (PMID 33276795, 2020).
metastatic prostate carcinoma (1 paper, 2024). A carcinoma that arises from the prostate gland and has spread to other anatomic sites. "Initially, we observed that the expression of HSPB6 was significantly lower in metastatic prostate cancer (lymph node metastases or distant metastases) compared to non-metastatic prostate cancer." (PMID 38374143, 2024).
osteosarcoma (1 paper, 2023). A usually aggressive malignant bone-forming mesenchymal neoplasm, predominantly affecting adolescents and young adults. "However, the association between osteosarcoma and HSPB6 remained unclear." (PMID 37861934, 2023). "As indicated by the findings, HSPB6 overexpression inhibits osteosarcoma growth and lung metastasis in vivo." (PMID 37861934, 2023). "As indicated by the result, HSPB6 overexpression was likely to prevent osteosarcoma growth and lung metastasis in vivo." (PMID 37861934, 2023). "It is noteworthy that although we discovered HSPB6 plays the role in inhibiting the progress of osteosarcoma." (PMID 37861934, 2023). "As indicated by the RNA-seq analysis, DEGs were primarily enriched in the MAPK pathway, and western blotting assay suggested that p-ERK1/2 protein expression in osteosarcoma cells was down-regulated after HSPB6 overexpression." (PMID 37861934, 2023). "CCK-8 and colony formation results show that osteosarcoma cells growth was reduced following HSPB6 overexpression." (PMID 37861934, 2023). "The RNA-seq was conducted after HSPB6 overexpression in osteosarcoma cells to search the potential mechanism and function of HSPB6 in osteosarcoma." (PMID 37861934, 2023). "And we found that HSPB6 overexpression decreased osteosarcoma progression through the ERK signaling pathway." (PMID 37861934, 2023). "Subsequently, HSPB6 was overexpressed in osteosarcoma cells, and its effect on biological behavior of osteosarcoma cells was observed." (PMID 37861934, 2023). "Next, the expression of HSPB6 was decreased in osteosarcoma tissues and HSPB6 mRNA expression was down-regulated in osteosarcoma cells MNNH/HOS and U2OS relative to osteoblast cells hFOB 1.19." (PMID 37861934, 2023). "The xenograft tumor model was employed to examine the effect of HSPB6 overexpression on the growth and metastasis of osteosarcoma in vivo." (PMID 37861934, 2023). "It was discovered that the expression of HSPB6 is low in other tumors And IHC assay show that HSPB6 expression decreased in osteosarcoma tissues." (PMID 37861934, 2023). "The results suggested that HSPB6 overexpression can inhibit the proliferation, migration, invasion, and increased apoptosis in osteosarcoma by suppressing the ERK signaling pathway." (PMID 37861934, 2023). "As revealed by the imaging of the osteosarcoma tumors, HSPB6 overexpression suppressed tumor development." (PMID 37861934, 2023). "Next, RT-qPCR results suggested the significantly lower HSPB6 mRNA expression in osteosarcoma cells MNNG/HOS and U2OS compared with osteoblast cells hFOB 1.19." (PMID 37861934, 2023). "As indicated by the result of CCK-8 and colony formation assays, HSPB6 overexpression was likely to inhibit the osteosarcoma cells proliferation, whereas the flow cytometry analysis suggested that apoptosis of osteosarcoma cells was increased after HSPB6 overexpression." (PMID 37861934, 2023). "Moreover, the western blotting assay suggested that the protein level of p-ERK1/2 was down-regulated in osteosarcoma when HSPB6 was overexpressed." (PMID 37861934, 2023). "First, clinical data may help us to explore the relationship between HSPB6 expression and osteosarcoma patients prognosis." (PMID 37861934, 2023). "In comparison to HSP90, HSP70 and HSP27 in osteosarcoma, the effect of HSPB6 on osteosarcoma was unknown." (PMID 37861934, 2023). "Second, if HSPB6 overexpression have an impact on osteosarcoma drug resistance, it may be better for clinical application." (PMID 37861934, 2023). "The link between HSPB6 and osteosarcoma was thus examined using functional assays." (PMID 37861934, 2023). "In this study, the effect of HSPB6 on osteosarcoma was validated through numerous experiments." (PMID 37861934, 2023). "Finally, we expect to further explore mechanism of HSPB6 regulation of osteosarcoma in future studies." (PMID 37861934, 2023).
osteosarcoma (continued). "Heat shock protein B6 (HSPB6) plays a certain role in the formation of several cancers, whereas its effect on osteosarcoma remains unclear." (PMID 37861934, 2023). "After HSPB6 overexpression, osteosarcoma cells achieved enhanced apoptosis." (PMID 37861934, 2023). "Furthermore, transwell and wound healing assays suggested that when HSPB6 was overexpressed, osteosarcoma cells migration and invasion were declined." (PMID 37861934, 2023). "Furthermore, western blotting assay was performed, and result suggested that the protein level phosphorylation-ERK1/2 (p-ERK1/2) was suppressed in osteosarcoma cells when HSPB6 was overexpressed, whereas the protein level of ERK1/2 did not vary significantly." (PMID 37861934, 2023). "As indicated by the results of this study, HSPB6 was down-regulated in osteosarcoma, and HSPB6 overexpression was likely to reduce the proliferation, migration, invasion and lung metastasis of osteosarcoma and boost osteosarcoma apoptosis through the ERK signaling pathway." (PMID 37861934, 2023). "Besides, transwell assay suggested that the migration and invasion of osteosarcoma cells was suppressed by HSPB6 overexpression, and wound healing experiment also found that HSPB6 overexpression inhibited osteosarcoma cells migration." (PMID 37861934, 2023). "Based on previous research, HSPB6 may serve as a future therapeutic target for osteosarcoma." (PMID 37861934, 2023). "Besides, the effect of HSPB6 on osteosarcoma in vivo was examined." (PMID 37861934, 2023). "As revealed by the findings of this study, HSPB6 overexpression exerted anticancer effects in osteosarcoma through the ERK signaling pathway and HSPB6 may be suitable target for osteosarcoma molecular therapies." (PMID 37861934, 2023). "Thus, the correlation between HSPB6 and ERK signaling pathway in osteosarcoma was explored." (PMID 37861934, 2023).
pancreatic cancer (1 paper, 2025). "Studies conducted on pancreatic cancer cell lines and cancer-associated fibroblasts (CAFs) have shown that increased HSPB6 expression in CAFs may contribute to the modulation of the tumor stroma." (PMID 41148842, 2025). "Low-molecular-weight heat shock proteins (lmHSPs), including HSP27, HSPB2, HSPB6, and αA-crystallin, play a complex role in the biology of pancreatic cancer by exhibiting both pro- and anti-tumorigenic effects." (PMID 41148842, 2025).
pancreatic ductal adenocarcinoma (1 paper, 2025). An infiltrating adenocarcinoma that arises from the epithelial cells of the pancreas. "For example, increased HSPB6 expression correlates with a more favorable prognosis in patients with pancreatic ductal adenocarcinoma." (PMID 41148842, 2025).
Parkinson disease (1 paper, 2025). A progressive degenerative disorder of the central nervous system characterized by loss of dopamine producing neurons in the substantia nigra and the presence of Lewy bodies in the substantia nigra and locus coeruleus. "There are not many studies regarding the HspB6 role in Parkinson’s disease." (PMID 40003991, 2025). "Like HspB6, HspB8’s role in Parkinson’s disease has not been the subject of many studies." (PMID 40003991, 2025).
schizophrenia (1 paper, 2024). A major psychotic disorder characterized by abnormalities in the perception or expression of reality. "Besides, PDE4A was related to heat shock protein B6 (HSPB6), aldehyde dehydrogenase 7A1 (ALDH7A1), A-kinase anchoring protein 1 (AKAP1), adrenoceptor beta 2 (ADRB2), SAG (an arrestin family member which desensitizes GPCR) and DISC1 (disrupted in Schizophrenia 1)." (PMID 38514754, 2024).
schwannoma (1 paper, 2013). A benign, usually encapsulated slow growing tumor composed of Schwann cells. "In our series, 5 HSPs were deregulated (HSPA12A: 3.31-fold, p=4.34e-4; HSPA13: 2.54-fold, p=0.0035; HSPA4L: 2.38-fold, p=1.17e-4; HSPB6: −2.19-fold, p=5.76e-4; HSPB8: −3.77-fold, p=0.001), suggesting that the CAV1/HSPs interaction may also play a role in schwannomas." (PMID 23354516, 2013).
stomach adenocarcinoma (1 paper, 2019). "In the stomach adenocarcinoma dataset, strong positive correlations in gene expression were identified between members of the small HSP family, including HSPB2, HSPB5 (CRYAB), HSPB6, HSPB7 and HSPB8, as well as the HSP40 family member DNAJB5, with superoxide dismutase (SOD3)." (PMID 30578123, 2019).
vacuolar myopathy (1 paper, 2026). "The identified HSPB6 variants are most likely the cause of the muscle disease in this family, thus identifying HSPB6 mutations as a novel cause of vacuolar myopathy." (PMID 41294008, 2026).
tumor (22 papers, 2013 to 2025). "In vivo experiments complement these findings, demonstrating HSPB6's tumor-suppressive efficacy by reducing tumor growth, thereby highlighting HSPB6 as a promising therapeutic target for BLCA." (PMID 39608715, 2024). "EdU assays illustrated that TCF7L1 overexpression diminished tumor cell proliferation, a phenomenon mitigated upon concurrent HSPB6 depletion." (PMID 39608715, 2024). "Conversely, knocking down HSPB6 expression partly reversed these effects, suggesting the tumor-suppressive impact of TCF7L1 overexpression is modulated by HSPB6 expression levels." (PMID 39608715, 2024). "In vivo experiments further validated HSPB6's tumor-suppressive role, as its overexpression weakened tumor growth." (PMID 39608715, 2024). "Studies have demonstrated that HSPB6 exhibits tumor-suppressive properties and can inhibit the progression of various cancers, such as liver cancer, ovarian cancer, and so on." (PMID 38374143, 2024). "In conclusion, we identified the C11 cluster in fibroblasts that specifically expressed HSPB6 as the essential cluster for PAAD development and constructed a nine-gene prognostic model through tumor-associated PAAD prognostic genes in the C11 subpopulation." (PMID 37588985, 2023). "Next, PCNA and MMP-2 expression was down-regulated following HSPB6 overexpression, suggesting the reduced ability of the tumor for migration and proliferation." (PMID 37861934, 2023). "HSPB6 inhibits apoptosis of murine tumor cells and protects against oxidative damage, while AKT1 helps mediate cell survival and clonogenic potential." (PMID 37009487, 2023). "Accumulating evidence has indicated that changes in HSPB6 DNA methylation levels during tumor formation have been observed, affecting its gene expression, as well as having an aberrant expression in several cancers, including CC." (PMID 37241227, 2023). "Among them, we identified and experimentally confirmed a group of methylation driver genes (e.g., PCDH17, IRX1, TBX5 and HSPB6) that play a critical role in neoplasia initiation, promotion, and progression." (PMID 33859751, 2021). "Moreover, analysis of data from the Clinical Proteomic Tumor Analysis Consortium (CPTAC) revealed that high HSPB6 expression correlates with longer overall survival in patients with PDAC, indicating its potential as a prognostic marker." (PMID 41148842, 2025). "Despite the established tumor-suppressing properties of HSPB6 in BLCA, as evidenced through both in vivo and in vitro studies, bioinformatics analyses have revealed a paradox: HSPB6 expression is notably higher in normal tissues compared to its reduced levels in cancerous counterparts." (PMID 39608715, 2024). "Interestingly, this tumor-suppressing effect can be enhanced by supplementing with 8-Br-cGMP, which increases HSPB6 phosphorylation." (PMID 38374143, 2024). "Recognizing the essential role of the PI3K/AKT/mTOR signaling pathway in tumor growth, which influences key cellular functions including survival, proliferation, metabolism, invasion, and angiogenesis, we explored how overexpressing HSPB6 affects this pathway." (PMID 39608715, 2024). "Additionally, alterations in the expression of key proteins associated with the PI3K/AKT/mTOR and EMT pathways, including p-PI3K, p-AKT, p-mTOR, E-cadherin, N-cadherin, and Slug, further substantiate the regulatory role of HSPB6 in modulating tumor dynamics." (PMID 39608715, 2024). "HSPB6 has a suppressive role in preventing CC tumor growth, and its depletion could stimulate CC progression through several mechanisms." (PMID 37241227, 2023). "TUNEL experiment also revealed that HSPB6 overexpression can promote tumor apoptosis." (PMID 37861934, 2023). "This suggests the possible role of HSPB6 in tumor progression." (PMID 37241227, 2023). "In summary, this study reveals that the expressions of HSPB6 and TCF7L1 are both downregulated in the tumor tissues of BLCA patients." (PMID 39608715, 2024).
tumor (continued). "Heat shock protein family B [small] member 6 (HSPB6), widely found in various muscles, has been recently identified as a tumor suppressor gene." (PMID 38374143, 2024). "STXBP6 mRNA expression was downregulated in 66.67% of tumor tissues, BCL6B was downregulated in 69.23%, FZD10 was downregulated in 71.79%, and HSPB6 was downregulated in 74.36% (p <0.001)." (PMID 30286088, 2018). "STXBP6 protein expression was downregulated in 91.43% of tumor tissues, BCL6B was downregulated in 88.57%, FZD10 was downregulated in 88.57%, and HSPB6 was downregulated in 91.43% (p <0.001, the original blots of western blots is shown in the S1–S8 Figs)." (PMID 30286088, 2018). "In agreement with our results, HSPB6 and HSPB7 have been found downregulated in several tumour types, and we report here this downregulation in all subtypes of BRCA is possibly supporting a role as tumour suppressor genes." (PMID 29954368, 2018). "Conversely, the role of HSPB6 in BLCA has remained unexplored until this study, which is the first to document the significant underexpression of HSPB6 in BLCA tissue samples and cell lines, unveiling its tumor-suppressive potential." (PMID 39608715, 2024). "Utilizing pan-cancer sequencing data from the TCGA database, we explored the expression levels of HSPB6 across a spectrum of tumor types and their corresponding normal tissues." (PMID 39608715, 2024). "However, expression levels of DNAJB1 (p = 0.018), HSPB2 (p < 0.001), HSPB6 (p < 0.001) and HSPA1A (p = 0.021) were significantly lower in tumor tissues." (PMID 31222140, 2019). "The methylation and expression validation results identified 4 candidate genes (STXBP6, BCL6B, FZD10, and HSPB6) that were significantly hypermethylated and downregulated in most of the tumor tissues compared with the noncancerous lung tissues." (PMID 30286088, 2018). "In addition, FXYD1 and HSPB6 were overexpressed only in KIRC and LIHC, respectively, whereas they were downregulated in other types of tumor." (PMID 26655252, 2016). "More than half of the genes were not DE in any tumor type, while seven genes (C7, ADH1B, HSPB6, FXYD1, PLAC9, TMEM132A and ASF1B) were DE in all tumor types." (PMID 26655252, 2016).
cancer (12 papers, 2014 to 2024). A tumor composed of atypical neoplastic, often pleomorphic cells that invade other tissues. "Although HSPB6 has the function of decreasing cell immigration, it has also been associated with poor outcomes in bladder cancer and contributes to cancer growth in esophageal cancer." (PMID 37241227, 2023). "Previous investigations have revealed hypermethylation of the HSPB6 promoter affects its function, but the transcriptional regulation of HSPB6 in cancer remains unexplored." (PMID 38374143, 2024). "Using an integrative approach of bioinformatics, RNA sequencing, and cell-based assays, we show that HSPB6 upregulation inhibits cancer cell proliferation and metastasis while promoting apoptosis." (PMID 39608715, 2024). "We noted that there was an adverse association between HSPB6 and HSPB1, where the expression of HSPB1 was elevated in most cancers and that of HSPB6 was decreased." (PMID 37241227, 2023). "In this investigation, we found, for the first time, that HSPB6 expression was downregulated in cancer tissues compared to its adjacent normal tissues and that its expression was decreased in DMH-induced colon tissues in an in vivo study." (PMID 37241227, 2023). "Studies have confirmed the critical function of HSPB6 in the endothelial proliferation and migration of various cancers." (PMID 34930465, 2021). "The downregulation of TCF7L1 in BLCA tissues contributes to diminished HSPB6 expression, suggesting that enhancing TCF7L1 activity could serve as a strategic avenue for upregulating HSPB6, thereby potentially inhibiting cancer progression." (PMID 39608715, 2024). "HSPB6 plays a crucial role in the synergistic cancer suppression of quinidine and 8-Br-cGMP." (PMID 38374143, 2024). "However, our experiments have solidly demonstrated HSPB6's robust anti-cancer activity in BLCA, reinforcing its potential as a pivotal factor in cancer biology." (PMID 39608715, 2024). "Interestingly, we found that overexpression of HSPB6 based on E2F1 overexpression could inhibit the cancer-promoting ability of E2F1." (PMID 38374143, 2024). "The observed decrease in HSPB6 expression pattern was further validated in paired cancerous and adjacent non-cancerous tissue samples obtained from patients undergoing radical cystectomy at our institution, thus confirming its diminished presence in cancer tissues." (PMID 39608715, 2024). "Additionally, HSPB1 expression is eliminated when HSPB6 is present in different cancer cell lines, and the interruption of heterodimer formation between HSPB1 and HSPB6 may lead to disease severity." (PMID 37241227, 2023). "Moreover, HSP20 (HSPB6) expression has been linked to several cancers and was absent in CC." (PMID 37241227, 2023). "About 80% (65/82) of HSPs showed aberrant expression, ranging from one cancer type (e.g., DNAJC25) to 15 cancer types (e.g., HSPB6)." (PMID 33225964, 2020). "Moreover, TCF7L1-mediated upregulation of HSPB6 leads to suppression of the PI3K/AKT/mTOR signaling pathway, a key driver of cancer progression." (PMID 39608715, 2024). "The results of UALCAN database analysis showed that the mRNA expression levels of CALR, CREB3L3, FBOX6, and KDELR3 were increased in cancer tissues compared with normal tissues, while the mRNA expression levels of CRYAB, DNAJB4, and HSPB6 were decreased in BLCA." (PMID 34930465, 2021).
myopathy (3 papers, 2024 to 2026). A disease of the muscle in which the muscle fibers do not function properly. "Interestingly, mutations in chaperones like Bag356 and DnaJB657 cause congenital muscle defects, and HSPB6, HSP70 and HSP90 are upregulated upon cardiac failure, pointing to the importance of an efficient PQC system to prevent myosin-related myopathies." (PMID 39054317, 2024).
neurodegenerative disease (1 paper, 2020). A disorder of the central nervous system characterized by gradual and progressive loss of neural tissue and neurologic function. "Out of 10 mammalian sHSPs, four family members are expressed in neurons and play a role in neurodegenerative diseases: HSPB1, HSPB5, HSPB8 and to a lower extend, HSPB6." (PMID 33330614, 2020).
neurological disorders (1 paper, 2020). "(B) cg05910615 lies in the TSS of HSPB6, which has been associated with neurological disorders." (PMID 33208194, 2020).